PRPSAP2 (phosphoribosyl pyrophosphate synthetase associated protein 2)
Description:
Seems to play a negative regulatory role in 5-phosphoribose 1-diphosphate synthesis.
Synonyms: PAP41
Tractability: PROTAC: ubiquitination databases record sites on it; its protein half-life has been measured.
Target class: Enzyme
Gene: Protein-coding gene on chromosome 17 (18,840,085 to 18,931,287, forward strand). Ensembl gene ENSG00000141127.
Subcellular location (Human Protein Atlas): Cytosol; Nucleoplasm
Gene Ontology:
Molecular function: identical protein binding; protein binding; enzyme inhibitor activity; enzyme regulator activity; magnesium ion binding
Biological process: 5-phosphoribose 1-diphosphate biosynthetic process; nucleobase-containing compound metabolic process; purine nucleotide biosynthetic process; nucleotide biosynthetic process
Cellular component: cytoplasm
Genetic constraint (gnomAD): Loss-of-function variants: 17 observed, 32.45 expected, observed/expected ratio (o/e) 0.52, 90% interval 0.36 to 0.79. The upper end of that interval is the gene's LOEUF score, 0.79, which puts it in group 3 of 6, group 1 being the genes least tolerant of losing a copy. Missense variants: 257 observed, 432.88 expected, observed/expected ratio (o/e) 0.59, 90% interval 0.54 to 0.66. Synonymous variants: 137 observed, 153.74 expected, observed/expected ratio (o/e) 0.89, 90% interval 0.77 to 1.03.
Homologues: Orthologues: chimpanzee PRPSAP2 (99% identical), macaque PRPSAP2 (99% identical), rat Prpsap2 (99% identical), mouse Prpsap2 (99% identical), guinea pig PRPSAP2 (99% identical), dog PRPSAP2 (95% identical), pig PRPSAP2 (94% identical), tropical clawed frog prpsap2 (89% identical), zebrafish prpsap2 (89% identical), rabbit PRPSAP2 (82% identical), Drosophila melanogaster CG2246 (66% identical), Caenorhabditis elegans W04G3.5 (58% identical). Paralogues in human: PRPSAP1 (76% identical), PRPS2 (43% identical), PRPS1 (42% identical), PRPS1L1 (42% identical).
Diseases named in the same sentence as PRPSAP2 in open-access papers:
PRPSAP2 is named in the same sentence as 10 diseases in open-access papers, as found by Europe PMC text mining. Sharing a sentence is not in itself a finding about the gene and the disease. The quoted sentences say what the papers report.
lymphoma (2 papers, 2025). A malignant (clonal) proliferation of B- lymphocytes or T- lymphocytes which involves the lymph nodes, bone marrow and/or extranodal sites. "We first confirmed that the PRPS isozymes co-assemble, together with the PRPS associated proteins (PRPSAP1, PRPSAP2), to form a complex in Myc-dependent lymphoma cells." (PMID 40446642, 2025).
osteosarcoma (2 papers, 2012). A usually aggressive malignant bone-forming mesenchymal neoplasm, predominantly affecting adolescents and young adults. "Although its oncogenic potential is not directly obvious, it is interesting to note that C17orf39 and also PRPSAP2 were recently found to be overexpressed in osteosarcoma cell lines." (PMID 22292074, 2012). "Its function in the skeleton is unknown, although a recent study proposed PRPSAP2 as a candidate oncogene in osteosarcoma tumorigenesis." (PMID 22876197, 2012). "Based on our statistical analysis of the correlation between copy number increase and expression level for each of the top ranking genes, we identified RICH2, c17orf45, TOP3A, COPS3, SHMT1, PRPSAP2, PMP22, and RASD1 as candidate osteosarcoma oncogenes in the 17p11.2-p12 region." (PMID 22292074, 2012). "However, prognostic studies for the other candidate genes require the development of new antibodies (C17orf39, RICH2, RASD1) or testing of available antibodies on osteosarcoma tissues (TOP3A, COPS3, SHMT1, PRPSAP2, PMP22), which is presently underway." (PMID 22292074, 2012).
cervical cancer (1 paper, 2022). A primary or metastatic malignant neoplasm involving the cervix. "The expression of circ_0004488, a circRNA generated from the PRPSAP2 gene, was much higher in the spheres than in the parental HeLa cells, indicating that a high expression of circ_0004488 may be involved in the acquisition of CSC-like characteristics in cervical cancer cells." (PMID 36439901, 2022).
glioma (1 paper, 2022). A benign or malignant brain and spinal cord tumor that arises from glial cells (astrocytes, oligodendrocytes, ependymal cells). "Furthermore, the expression of PRPS1, PRPS2, PRPSAP1 (PAP39) and PRPSAP2 (PAP41) genes in U87 glioma cells is not inhibited by ERN1 (EC 2.7.11, endoribonuclease activity of endoplasmic reticulum to nuclei-1)." (PMID 35741038, 2022).
meningioma (1 paper, 2017). A generally slow growing tumor attached to the dura mater. "The trends of gene expression profiles of candidates such as EFCAB2, EPS8L1, NOL3, PAIP1 and SNX1 showed elevated expression in meningiomas compared to controls, while CAMK2N1, CRYM and PRPSAP2 showed decreased expression levels in meningiomas compared to the controls." (PMID 28938569, 2017).
multiple myelomas (1 paper, 2012). "Overexpression of SHMT1 and PRPSAP2 (and also COPS3) has been reported to occur in multiple myelomas." (PMID 22292074, 2012).
osteogenesis imperfecta (1 paper, 2012). Osteogenesis imperfecta (OI) comprises a heterogeneous group of genetic disorders characterized by increased bone fragility, low bone mass, and susceptibility to bone fractures with variable severity. "Disorders of bone matrix as typified by osteogenesis imperfecta are characterized by bone that is weak and brittle with low BMC, and three of the strains (Prpsap2, Slc38a10, Sparc) displayed this phenotype." (PMID 22876197, 2012).
cancer (1 paper, 2022). A tumor composed of atypical neoplastic, often pleomorphic cells that invade other tissues. "GEPIA2 database analysis of 33 cancer types showed the following top 10 ALKBH5-related genes: GID4 (R=0.71), TOP3A (R=0.67), MAPK7 (R=0.66), NT5M (R=0.61), FLII (R=0.59), ZNF18 (R=0.57), DRG2 (R=0.57), COPS3 (R=0.56), MED9 (R=0.56) and PRPSAP2 (R=0.56) (all P<0.0001)." (PMID 35444654, 2022).
PRPSAP2 also shares sentences with these, for which no sentence is quoted: Alzheimer disease (1 paper); hyperuricemia (1).